LPL (lipoprotein lipase)
Diseases named in the same sentence as LPL in open-access papers (continued):
Sharing a sentence is not in itself a finding about the gene and the disease.
Insulin resistance (continued). "Among middle-aged healthy and prediabetic Japanese individuals, elevated insulin resistance leads to decreased LPL levels and increased HTGL levels in the peripheral bloodstream." (PMID 40507147, 2025). "The effect of insulin resistance on circulating LPL and HTGL levels is greater in females than in males." (PMID 40507147, 2025). "Decreased LPL activity, especially in those with the G gene, can lead to lipid buildup, increased TG, and consequent effects on blood pressure and insulin resistance, especially when combined with diets high in carbohydrates." (PMID 41372238, 2025). "In T2D, insulin resistance disrupts the activity of LPL, mainly in adipose tissue and the heart, leading to triglyceride accumulation and lipotoxicity." (PMID 41373652, 2025). "A high insulin resistance affected circulating levels of LPL and GPIHBP1 in the statin-treated groups." (PMID 40507147, 2025). "In diabetic patients, lipoprotein lipase impairment from insulin resistance yields atherogenic remnants, particularly burdensome in high-carb rural diets (rice/potato-heavy, fiber-poor)." (PMID 41573486, 2025). "These indicate that DTG and RAL reduce LPL levels through two mechanisms: a direct effect on LPL expression and an indirect effect by inducing insulin resistance through increased levels of the inflammatory cytokine such as IL-6." (PMID 41156460, 2025). "Prediabetes with insulin resistance (decreased insulin function) results in decreased lipolysis process and reduced lipoprotein lipase activity." (PMID 39081429, 2024). "Insulin resistance and insufficiency both have an impact on lipoprotein lipase, the primary enzyme that removes lipids from the bloodstream." (PMID 38926327, 2024). "Insulin resistance hampers the normal function of lipoprotein lipase, an enzyme crucial for triglyceride breakdown, leading to their accumulation." (PMID 38280039, 2024). "Insulin resistance reduces the activity of lipoprotein lipase (LPL), leading to increases in intermediate-density lipoprotein (IDL) and VLDL and decreases in HDL concentration." (PMID 38790963, 2024). "Crocetin inhibited insulin resistance and raised hepatic lipoprotein lipase activity in HFD-induced insulin resistance in rats." (PMID 38419885, 2024). "For example, increased LPL activity in the skeletal muscle of rats reduced obesity and insulin resistance in obese rats." (PMID 39590382, 2024). "Insulin resistance is closely tied to qualitative and quantitative lipid modifications, including reduced nuclear expression of lipoprotein lipase, altered function of hormone-sensitive lipase, and increased release of free fatty acids from adipocytes." (PMID 39201088, 2024). "Mice with reduced LPL concentration had higher fat mass and more insulin resistance, while mice with increased adipose LPL had the opposite." (PMID 38164484, 2024). "GLP-1RAs were also reported to improve insulin resistance, which elevates the activity of LPL and ameliorates the lipid profile." (PMID 36979848, 2023). "Insulin resistance reduces the activity of lipoprotein lipase (LPL), which, in turn, increases TG-rich lipoproteins such as intermediate-density lipoprotein (IDL) and VLDL and reduces HDL." (PMID 36979848, 2023). "Insulin resistance adversely affects enzymes such as LPL and hepatic lipase (HL), leading to conditions that are highly atherogenic, such as a decrease in HDL and increases in small-dense LDL (SdLDL) and remnant lipoproteins." (PMID 37895151, 2023). "The hormone can increase HDL while decreasing serum TG concentrations by improving insulin resistance and modulating lipoprotein lipase and hepatic lipase activity." (PMID 37371552, 2023). "Insulin resistance impairs the function of insulin-dependent hormone-sensitive lipase and lipoprotein lipase, which are involved in lipid metabolism, whereas insulin cannot act effectively due to obesity and dyslipidaemia." (PMID 37152969, 2023).
Insulin resistance (continued). "Excessive maternal TG-rich VLDL concentrations are likely driven by increased production in the liver and decreased clearance in maternal peripheral tissues due to reduced LPL activity, both related to insulin resistance." (PMID 36979405, 2023). "ANGPTL4 is a molecular linker between insulin resistance and rheumatoid arthritis and can inhibit LPL activity." (PMID 36790644, 2023). "Usually, overweight and moderate obesity are accompanied by normal LPL activity, whereas insulin resistance conditions show a decrease in this hydrolytic activity." (PMID 37108229, 2023). "When visceral fat increases, it will enhance the decomposition of visceral fat by lipoprotein lipase in adipose tissue, which leads to the production of excessive free fatty acids, leading to insulin resistance (IR) and MetS46,47." (PMID 37045908, 2023). "The expressions of FAS, ACC, and LPL genes were significantly reduced, and body weight gain, serum glucose, insulin levels, and insulin resistance were also significantly inhibited by 6-gingerol." (PMID 37050926, 2023). "Glucose tolerance and insulin resistance were remarkably improved in Ad-LPL-treated mice compared to those in control Ad vector-treated mice." (PMID 36099304, 2022). "To determine the effect of LPL overexpression on glucose metabolism in a mouse model of HFD-induced insulin resistance, we performed a glucose tolerance test two weeks after Ad vector administration." (PMID 36099304, 2022). "Body composition, the proportion of visceral fat, the role of lipoprotein lipase and of insulin resistance differ by ethnicity, probably related to genetics and/or epigenetics, and influence lipid and lipoprotein metabolism." (PMID 35331154, 2022). "LPL mass in human preheparin serum is suggested as a biomarker of obesity, insulin resistance, and dyslipidemia, and LPL mass is inversely related to the metabolic syndrome." (PMID 35147910, 2022). "Hepatic LPL overexpression suppressed lipid accumulation in the liver and improved glucose metabolism and insulin resistance." (PMID 36099304, 2022). "Insulin resistance leads to impaired glycogen synthesis and proteolytic metabolism in skeletal muscle, and inhibits lipoprotein lipase activity in adipocytes, resulting in the release of free fatty acids and inflammatory cytokines." (PMID 35548566, 2022). "Insulin resistance reduces glycogen synthesis and protein catabolism in skeletal muscles while inhibiting lipoprotein lipase activity in adipocytes, resulting in a higher release of free fatty acids and inflammatory cytokines." (PMID 35942179, 2022). "Insulin can mediate antilipolysis, but adipose tissue insulin resistance can reduce this effect, lowering lipoprotein lipase activity and further triggering hyperlipidemia." (PMID 35340412, 2022). "Increased insulin resistance further leads to reduced lipoprotein lipase and increased hepatic lipase, resulting in the decreased maturation and increased catabolism of HDL-C, respectively." (PMID 35711546, 2022). "In contrast to our findings, a previous study has reported that standard chow-fed transgenic mice with liver-specific overexpression of LPL exhibit increased hepatic lipid accumulation and insulin resistance." (PMID 36099304, 2022). "HOMA-IR, an index of insulin resistance, was also considerably lower in mice administered with Ad-LPL than in those administered with Ad-Luc." (PMID 36099304, 2022). "Insulin resistance also decreases the activity of LPL, the rate-limiting enzyme of the catabolism of TG-rich lipoproteins such as VLDL." (PMID 35203610, 2022). "More studies have shown that pre-heparin LPL mass negatively correlates with insulin resistance, which has been suggested as a biomarker for metabolic syndrome and related cardiovascular diseases." (PMID 36561774, 2022). "In white adipose tissue, increased LPL activity is related with increased fat mass, chronic inflammation and insulin resistance." (PMID 35734882, 2022).
Insulin resistance (continued). "The synergistic effects of elevated cellular cortisol and insulin, for example, on lipoprotein lipase activity, result in insulin resistance and impaired glucose control with elevated circulating free fatty acids." (PMID 33270115, 2021). "Since LPL is upregulated by insulin, any state of insulin resistance or diabetes mellitus will result in diminished LPL activity, elevated TG lipoproteins, and reduced HDL." (PMID 34299261, 2021). "Lipoprotein lipase, a key enzyme in the elimination and breakdown of TGs from the circulation, enzyme is alleviated by both insulin deprivation and insulin resistance." (PMID 34290966, 2021). "For example, in insulin resistance individuals with Type 2 diabetes (T2D), the lipoprotein lipase (LPL) is reduced leading to a decrease in plasma HDL-C and an increase in TGs and accumulation of VLDL." (PMID 34313294, 2021). "Patients with insulin resistance have delayed hydrolysis of TG-rich lipoproteins due to reduced lipoprotein lipase activity." (PMID 34354179, 2021). "It is also important to remember that in the final third of pregnancy there are usually reductions in FA synthesis and LPL activity and an increase in triglycerides and insulin resistance." (PMID 34198804, 2021). "During pregnancy, maternal insulin resistance leads to decreased lipoprotein lipase (LPL) activity and hence 2–3-fold increased maternal triglyceride levels." (PMID 33004027, 2020). "ApolipoproteinC3 (APOC3) is lipoprotein lipase (LPL) inhibitor that induces obesity and develops insulin resistance." (PMID 32899471, 2020). "In a group of 26 subjects varying in insulin sensitivity, insulin resistance was negatively correlated with adipose tissue LPL activity." (PMID 32504883, 2020). "Second, olanzapine-induced insulin resistance inhibits the activity of lipoprotein lipase, thereby slowing the catabolism of LDL and increasing plasma LDL-C levels." (PMID 33046806, 2020). "These cytokines induce insulin resistance in skeletal muscle, increase hepatic synthesis of pro-coagulant factors, inhibit lipoprotein lipase, and increase fatty acid oxidation, and atherogenic lipoprotein serum level." (PMID 33643281, 2020). "Both IL-6 and TNF-α promote insulin resistance inhibiting lipoprotein lipase (LPL), decreasing triglyceride hydrolysis into free fatty acids, and increasing triglyceride storage in adipocytes, resulting in larger fat cells." (PMID 33643281, 2020). "Existing data on the relation between insulin resistance and adipose tissue LPL activity are mixed as well." (PMID 32504883, 2020). "Vitamin D affects adipogenesis by regulating the expression of adipocyte transcription factors, such as PPARγ, C/EBPα, and LPL, and through affecting insulin resistance, VDR and unliganded VDR, and adipokine secretion." (PMID 32149047, 2020). "Insulin resistance promotes the increase of hormone-sensitive lipase activity of adipose tissue and the decrease of lipoprotein lipase activity." (PMID 31534451, 2019). "Transgenic mice expressing excess LPL in skeletal muscle, however, eventually develop lipotoxicity and insulin resistance." (PMID 30863636, 2019). "The Lipoprotein lipase (LPL) is a key enzyme in lipid metabolism and abnormalities in its function are associated with dyslipidemia, insulin resistance, and T2DM." (PMID 30445764, 2018). "This abnormality has as one of its features the higher circulating levels of LPL that leads to ectopic fat deposition in peripheral tissues and contributes to insulin resistance, hyperglycemia, and progressively to T2DM." (PMID 30445764, 2018). "Nevertheless, it is known that overexpression of LPL in hepatocytes can result into a 2-fold increase in liver TG content and insulin resistance in mice." (PMID 30024933, 2018). "Actually, overexpression of lipoprotein lipase gene has been related to fatty acid accumulation and insulin resistance." (PMID 28791008, 2017).
Insulin resistance (continued). "Improvements in insulin resistance and reductions in body weight increase lipoprotein lipase activity, which plays a key role in breaking down plasma TG from TG-rich lipoproteins, such as chylomicrons and very low density lipoproteins." (PMID 28621714, 2017). "It is known that glucose toxicity and strong insulin resistance induce inactivation of LPL, which results in chylomicronemia." (PMID 27652072, 2016). "Decreased lipoprotein lipase activity as a result of insulin resistance would also lead to accumulation of triglyceride-rich lipoproteins in plasma." (PMID 27433285, 2016). "LPL has been considered as a link between insulin resistance and atherosclerosis, given its role in controlling the delivery of free fatty acids to muscle, adipose tissue and vascular wall macrophages, wherein lipid uptake influences insulin sensitivity." (PMID 26999119, 2016). "The overexpression of Tnf is closely related to insulin resistance, reduced lipoprotein lipase activity, and increased lipase activity." (PMID 26881249, 2016). "Insulin resistance is also associated with increased plasma levels of ApoC-III, an inhibitor of LPL." (PMID 25725623, 2015). "It has been reported that low LPL reflects insulin resistance and that LPL expression increased in diabetic patients with an average body mass index of 25.1 (the Japanese obesity criteria) with angiotensin receptor type 1 (ATR1) blocker treatment." (PMID 26447765, 2015). "Lipoprotein lipase activity is insulin-dependent and insulin resistance among smokers was observed in many studies." (PMID 26068452, 2015). "Both insulin deprivation and insulin resistance attenuate the activity of lipoprotein lipase, a key enzyme in the removal and degradation of triglycerides from circulation." (PMID 26003803, 2015). "TZDs can decrease insulin resistance, modify adipocyte differentiation, and induce lipoprotein lipase (LPL) by regulating the expression of PPARγ target genes." (PMID 24473166, 2014). "TG-mediated changes in very-low-density lipoprotein and lipoprotein lipase activity ultimately lead to increased expression of angiopoietin-like protein 4, and thus, insulin resistance." (PMID 24455201, 2013). "LPL varied inversely with the average arterial blood pressure (g), reinforcing the state of insulin resistance typical of the metabolic syndrome that characterized the low-HDL-C cases; however, potential genetic reasons for this association cannot be ignored." (PMID 24267726, 2013). "Insulin resistance tends to gain TG levels and reduce lipoprotein lipase activity, which boost HDL-C levels." (PMID 24453904, 2013). "LPL dysfunction can increase the amount of FFAs in the body and further contribute to insulin resistance." (PMID 24086538, 2013). "We conclude that expression and distribution of LPL in mouse pancreatic tissue appears relatively robust with respect to nutritional state and to metabolic disturbances connected to obesity and insulin resistance." (PMID 23186339, 2012). "In this study, high levels of FAS and LPL activity detected in subjects with steatosis are in agreement with the presence of insulin resistance evaluated in same subjects." (PMID 23110339, 2012). "In women with obesity, there is an increased production of FFA and decreased activity of LPL as a result of the prominent insulin resistance." (PMID 22262974, 2012). "Because insulin resistance also suppresses LPL activity and is an impediment to the catabolism of very low-density lipoprotein (VLDL), production of VLDL in the liver is increased and hyperlipidemia occurs." (PMID 19398847, 2009). "Insulin resistance resulting from obesity decreases lipoprotein lipase (LPL) activity, and then, a reduced LPL activity leads to the decreased clearance of fasting and postprandial TG-rich lipoproteins and to the decreased production of HDL." (PMID 18072966, 2007).
Insulin resistance (continued). "Furthermore, insulin resistance impairs the activity of lipoprotein lipase, thereby reducing the breakdown of TGs and elevating TG levels." (PMID 40996074, 2025). "This substrate-driven secretion, together with the transient insulin resistance and reduced peripheral lipoprotein lipase activity observed during early GH exposure, offers a plausible biological explanation for the modest, non-significant TG elevation documented in the present study." (PMID 41347132, 2025). "Insulin resistance leads to an inhibition of lipoprotein lipase (LPL) which, along with increased cholesteryl ester transfer protein (CETP) activity, causes an increase in circulating small low-density lipoprotein (LDL) and large very-low-density lipoprotein (VLDL) particles." (PMID 41156274, 2025). "Further, circulating GPIHBP1 levels may be affected by renal function and in a compensatory manner in response to a decrease in circulating LPL levels correlated with insulin resistance." (PMID 40507147, 2025). "Growth hormone inhibits activity of the lipoprotein lipase in adipose tissue, increasing the efflux of free fatty acids to the liver, and therefore promoting the insulin resistance, increased synthesis of triglycerides, and reduced high-density lipoprotein (HDL) levels, and body fat." (PMID 40088375, 2025). "The positive correlation between circulating levels of HTGL and GPIHBP1 could be explained by an increase in GPIHBP1 levels, which may compensate for the decrease in LPL levels attributed to increased insulin resistance." (PMID 40507147, 2025). "There are gender differences in LPL levels in peripheral bloodstream and insulin resistance." (PMID 41156460, 2025). "Insulin resistance has a greater effect on circulating LPL levels in females than in males." (PMID 40507147, 2025). "We recently reported that greater insulin resistance was associated with lower levels of LPL and HDL-C, but not higher HOMA-β, in non-HIV controls." (PMID 41156460, 2025). "Thus, determining the molecular networks that modulate LPL expression due to insulin resistance, inflammation, and oxidative stress will be critical to tailoring predictors for enhancing LPL function in diabetics." (PMID 41373652, 2025). "Furthermore, in human adipose tissue, the integrase inhibitors dolutegravir (DTG) and raltegravir (RAL) induce insulin resistance and suppress LPL mRNA expression." (PMID 41156460, 2025). "Insulin resistance contributes to reducing the activity of lipoprotein lipase (LPL) and hepatic lipase, increasing plasmatic concentrations of atherogenic lipoproteins, such as small dense low-density lipoproteins (sdLDLs) and very low density lipoproteins (VLDLs)." (PMID 40869400, 2025). "These biochemical and physical aberrations could be consequences for the underlying diminished lipoprotein lipase activity and increased HDL catabolism associated with insulin resistance." (PMID 38846018, 2024). "DKA due to insulin resistance or insulin deficiency can result in increased lipolysis of adipose tissue, increased free fatty acid release and very low-density lipoprotein (VLDL) production, and decreased lipoprotein lipase activity." (PMID 39421549, 2024). "Insulin resistance is one of the factors that inhibits the activity of LPL." (PMID 39335757, 2024). "Furthermore, peripheral insulin resistance and accumulation of lipids were the outcomes of overly expressed lipoprotein lipase (LPL) within the liver or muscles." (PMID 39807459, 2024). "It has been observed, indeed, that LPL activity in skeletal muscle negatively correlates with plasma insulin levels and it has been suggested that it could be lowered by insulin resistance." (PMID 38674801, 2024).